Y_RNA (Y RNA )
Gene: Miscellaneous RNA gene on chromosome 17 (75,089,862 to 75,089,974, reverse strand). Ensembl gene ENSG00000206713.
Homologues: Orthologues: chimpanzee Y_RNA (99% identical), macaque Y_RNA (81% identical). Paralogues in human: RNY1 (84% identical), RNY1P11 (82% identical), Y_RNA (82% identical), Y_RNA (81% identical), Y_RNA (80% identical), RNY1P8 (79% identical), Y_RNA (79% identical), Y_RNA (78% identical), Y_RNA (77% identical), RNY1P10 (76% identical), Y_RNA (76% identical), RNY1P15 (75% identical), and 96 more.